RNU4-75P (RNA, U4 small nuclear 75, pseudogene)
Gene: Small nuclear RNA gene on chromosome 1 (99,784,740 to 99,784,885, reverse strand). Ensembl gene ENSG00000201491.
Homologues: Orthologues: chimpanzee U4 (99% identical), macaque U4 (94% identical), pig U4 (56% identical), dog U4 (53% identical), guinea pig U4 (53% identical), rat LOC120102557 (47% identical). Paralogues in human: RNU4-84P (78% identical), RNU4-70P (71% identical), RNU4-17P (68% identical), RNU4-85P (64% identical), RNU4-28P (63% identical), RNU4-32P (61% identical), RNU4-50P (61% identical), RNU4-10P (60% identical), RNU4-15P (60% identical), RNU4-49P (59% identical), RNU4-36P (57% identical), RNU4-69P (57% identical), and 81 more.